MNDA (myeloid cell nuclear differentiation antigen)
Diseases named in the same sentence as MNDA in open-access papers:
MNDA is named in the same sentence as 50 diseases in open-access papers, as found by Europe PMC text mining. Sharing a sentence is not in itself a finding about the gene and the disease. The quoted sentences say what the papers report.
lung carcinoma (3 papers, 2022 to 2023). "Additionally, hsa-miR-33a-5p and hsa-miR-33b-5p directly targeted the MNDA promoter, which may be the main reason for the down-regulation of MNDA expression in lung cancer." (PMID 36101427, 2022). "Hub genes including LRRK2, BMI1, MNDA (myeloid cell nuclear differentiation antigen), OTX1, FFAR2, and PITX1 play a significant role in lung cancer progression." (PMID 38137330, 2023). "To further explore the mechanism of MNDA down-regulation in LA, we predicted that SPI1 is the transcriptional regulator of MNDA, that SPI1 is significantly down-regulated in lung cancer, and that MNDA expression increases with the increase in SPI1 expression." (PMID 36101427, 2022).
osteosarcoma (3 papers, 2014 to 2024). A usually aggressive malignant bone-forming mesenchymal neoplasm, predominantly affecting adolescents and young adults. "In this study, we observed that MNDA mRNA was significantly less abundant in Saos-2 cells compared to U937 cells, confirmation of the downregulation of MNDA expression in human osteosarcoma." (PMID 24520299, 2014). "To the best of our knowledge, we are the first group to have observed MNDA overexpression-mediated cell growth inhibition, cell cycle arrest/apoptosis and reduced invasiveness in osteosarcoma cells." (PMID 24520299, 2014). "Our results demonstrated that the overexpression of MNDA affected osteosarcoma cells by effectively inhibiting proliferation, inducing apoptosis and reducing their migration in vitro." (PMID 24520299, 2014). "In conclusion, the present study further confirmed the downregulation of MNDA in osteosarcoma cells as demonstrated in our previous study and has demonstrated that the overexpression of MNDA in osteosarcoma cells results in growth inhibition, cell cycle arrest, apoptosis and reduced invasiveness." (PMID 24520299, 2014). "Moreover, hsa-miR-889-3p has been shown to target genes such as MNDA and KLF9 to promote cell growth and proliferation in osteosarcoma and non-small cell lung cancer, respectively." (PMID 39684278, 2024).
viral infections (3 papers, 2020 to 2024). "While the relevance of PYHIN1 and MNDA in restricting viral infections in vivo remains to be determined, our results clearly demonstrate that they are about as effective as IFI16 in restricting HIV-1 in primary macrophages." (PMID 32760121, 2020). "Given the apparent specificity of MNDA for IRF7 induction, and the cell type-specific expression of MNDA, this PYHIN could be a key target either to boost type I IFN during a viral infection, or to inhibit dysregulated type I IFN during autoimmunity." (PMID 35013241, 2022).
atherosclerosis (2 papers, 2025). A disease characterized by the build-up of fatty material and calcium deposition in the arterial wall resulting in partial or complete occlusion of the arterial lumen. "A bioinformatic analysis and machine learning algorithms approach illustrated that 5 hub genes (SPI1, MMP9, C1QA, CX3CR1, MNDA) could predict the risk of atherosclerosis in SLE." (PMID 40725777, 2025). "We identified 12 lactylation-related genes that are more reliably associated with atherosclerosis: five upregulated genes (LSP1, IKZF1, MNDA, RCC2, and WAS) and seven downregulated genes (CSRP2, PPP1CB, CSRP1, HEXIM1, CALD1, PDLIM1, and RANBP2)." (PMID 40248193, 2025).
autoimmune conditions (2 papers, 2024 to 2025). "MNDA regulates the pathogen-induced type I interferon cascade in human monocytes, essential for anti-viral reactions, and also instigates autoimmunity in cases of dysregulation." (PMID 39364409, 2024).
chronic lymphocytic leukemia (2 papers, 2020 to 2022). "MNDA and MAGEB4 (- methylation) are myeloid cell differentiation antigen involved in chronic lymphocytic leukemia and other cancers and cancer-testis antigens associated with immunotherapy treatment responses and undergoing aberrant methylation." (PMID 36812605, 2022). "MNDA, which is expressed in subgroups of chronic lymphocytic leukemia, diffuse large B-cell lymphoma, and mantle-cell lymphoma and especially expressed by lymphomas derived from the marginal zone, can be used as a useful marker for nodal marginal zone lymphoma." (PMID 33042984, 2020).
COVID-19 (2 papers, 2024). A disease caused by infection with severe acute respiratory syndrome coronavirus 2. "Moreover, we identified several other inflammation-related proteins that are linked to COVID-19, such as CD209, CD58, CCL15, CCL28, and MNDA." (PMID 38575325, 2024). "Seven common key genes were found in these four hub gene sets, including FCER1G, ITGAM, LCP2, LILRB2, MNDA, SPI1, and TYROBP, which were considered core targets of IC and COVID-19." (PMID 38267482, 2024).
lymphoma (2 papers, 2020 to 2024). A malignant (clonal) proliferation of B- lymphocytes or T- lymphocytes which involves the lymph nodes, bone marrow and/or extranodal sites. "In addition, new analysis predicted lymphoma subtypes using cell-of-origin markers that hematopathologists use in the clinical routine, including CD3, CD5, CD19, CD79A, MS4A1 (CD20), MME (CD10), BCL6, IRF4 (MUM-1), BCL2, SOX11, MNDA, and FCRL4 (IRTA1)." (PMID 38745770, 2024).
myelodysplastic syndrome (2 papers, 2022 to 2024). A clonal hematopoietic disorder characterized by dysplasia and ineffective hematopoiesis in one or more of the hematopoietic cell lines. "The elevated expression of MNDA is a marker of various forms of myelodysplastic syndromes (MDS), which comprise erythro-myelopoiesis disorders." (PMID 38680493, 2024). "Reduced levels of MNDA gene transcripts have been detected in familial and sporadic cases of myelodysplastic syndrome (MDS)." (PMID 36101427, 2022).
periodontitis (2 papers, 2022 to 2026). An acute or chronic inflammatory process that affects the tissues that surround and support the teeth. "In terms of the shared molecular mechanisms underlying periodontitis and renal cell carcinoma, six genes (IKZF1, LGALS1, LSP1, MNDA, VIM and WAS) were consistently upregulated in both disease tissues, indicating their potential involvement in the common pathogenesis of the two diseases." (PMID 42157182, 2026).
Sepsis (2 papers, 2022 to 2023). Sepsis is defined as life-threatening organ dysfunction caused by a dysregulated host response to infection. "However, only a small part of MVPs have relatively large Δβ (|Δβ|> 0.2), and focusing on those with large Δβ, we found that 6 of 26 differentially methylated genes (23.1%) were previously associated with sepsis in the literature, including ALK, ZEB2, MNDA, AIM2, TLR5, and JUNB." (PMID 35242787, 2022). "MNDA is an IFN-induced gene with regulatory effects including regulation of myeloid differentiation and induction of apoptosis as a means of decreasing acute inflammation in conditions such as sepsis." (PMID 37471165, 2023).
breast carcinoma (1 paper, 2012). "Gene expression validation for MEF2C and MNDA in breast cancer samples." (PMID 22952604, 2012). "In this paper, we have analyzed the role that thermodynamic fluctuations in energy at the cell-level play in the synthesis of transcription factors MNDA, POU2AF1, MEF2C and SMAD3 and how can this energetic constrains be related with the presence of primary breast carcinomas." (PMID 22952604, 2012).
emphysema (1 paper, 2021). "The “response to stress” DEGs unique for E-dominant COPD include genes associated with neutrophils like CSF3R, MNDA and CXCL122–24 and this suggests that neutrophils might be selectively increased in the airway brush samples from emphysema-dominant disease." (PMID 34145303, 2021).
hepatoma (1 paper, 2024). "MNDA is expressed only in myeloid rather than hepatoma cell lines." (PMID 38904028, 2024).
hyperglycaemia (1 paper, 2020). "MNDA is an inflammatory gene and is confirmed to be highly expressed in T1DM and hyperglycaemia." (PMID 32684073, 2020).
Hypertension (1 paper, 2021). The presence of chronic increased pressure in the systemic arterial system. "Two genes each from LEAD vs. CVD comparison were found to be linked to hypertension status (GLI4 and MNDA) and usage of statins (FAM167A and C1orf216) as well as 58 genes (54 and 4 from LEAD vs. CVD and AAA vs. CVD comparisons, respectively) were related to acetylsalicylic acid medication." (PMID 33801150, 2021).
influenza (1 paper, 2021). An acute viral infection of the respiratory tract, occurring in isolated cases, in epidemics, or in pandemics; it is caused by serologically different strains of viruses (influenzaviruses) designated A, B, and C, has a 3-day incubation period, and usually lasts for 3 to 10 days. "Among the most differentially expressed genes, myeloid cell nuclear differentiation antigen (MNDA) and cathepsin S (CTSS) were strongly upregulated in CD14+ monocytes after influenza vaccination." (PMID 34695164, 2021).
liver cancer (1 paper, 2021). An epithelial or non-epithelial malignant neoplasm that arises from the liver. "Notably, Myeloid Cell Nuclear Differentiation Antigen (MNDA) is at a high level in all the three topological metrics, suggesting it is an important transcriptional regulator in liver cancer." (PMID 33996828, 2021).
lung adenocarcinoma (1 paper, 2023). A carcinoma that arises from the lung and is characterized by the presence of malignant glandular epithelial cells. "Hsa-miR-33a-5p, which directly targets myeloid cell nuclear differentiation antigen (MNDA), a member of the hematopoietic protein family, was found to be upregulated in lung adenocarcinoma and was associated with poorer overall survival." (PMID 36979715, 2023).
meningioma (1 paper, 2020). A generally slow growing tumor attached to the dura mater. "Proteins involved in neutrophil degranulation, such as ARSA, GCA, FUCA1, PRTN3, ELANE, MNDA, and LCN2, were identified uniquely or with differential abundance in male meningiomas." (PMID 32587372, 2020).
mesothelioma (1 paper, 2025). A usually malignant and aggressive neoplasm of the mesothelium which is often associated with exposure to asbestos. "Noteworthy observations included a significant infiltration of M1 macrophages and CD4 + T cells in mesothelioma, with genes SOAT1, MNDA, and ITGAM showing a positive correlation with the level of M1 macrophage infiltration." (PMID 40223054, 2025).
mycobacterial infections (1 paper, 2017). "Whether, other members of ALR genes in humans (PYHIN1 and MNDA) which also have PYHIN and HIN domains may play a role in innate immune response during mycobacterial infections, needs further investigation." (PMID 28529930, 2017).
Obesity (1 paper, 2023). Accumulation of substantial excess body fat. "Our results indicate that in the GSE44000 obesity-related dataset, the expression levels of MNDA, TNC, CHIT1, and MMP9 exhibited significant differences." (PMID 37671970, 2023). "In this study, we constructed a co-expression network between obesity and PTC and identified four common hub genes (MNDA, TNC, CHIT1, MMP9) and two common TFs (ELF4, STAT3), which might provide new diagnostic and therapeutic strategies for obesity-related PTC." (PMID 37671970, 2023). "In conclusion, these four genes (MNDA, TNC, CHIT1, MMP9) may serve as a link between obesity and PTC and should be further examined in subsequent analyses." (PMID 37671970, 2023). "Based on our findings, it can be concluded that these four genes (MNDA, TNC, CHIT1, and MMP9) may have important biological roles in preventing and treating obesity and PTC." (PMID 37671970, 2023).
Parkinson disease (1 paper, 2025). A progressive degenerative disorder of the central nervous system characterized by loss of dopamine producing neurons in the substantia nigra and the presence of Lewy bodies in the substantia nigra and locus coeruleus. "Other notable observations include the downregulated levels of OSM, MNDA, AZU1 and MMP9, which are well-known neuroinflammatory markers, proven in several Parkinson’s disease models." (PMID 39816194, 2025).
psoriasis (1 paper, 2023). An autoimmune condition characterized by red, well-delineated plaques with silvery scales that are usually on the extensor surfaces and scalp. "Through TMT as one of isobaric labeling tags-based quantitative proteomic analysis and subsequent verification using ELISA, we especially identified three novel biomarkers associated with CVD risks in patients with psoriasis; CALD1, ZYX, and MNDA." (PMID 36804462, 2023). "Verification by ELISA revealed that caldesmon (CALD1), myeloid cell nuclear differentiation antigen (MNDA), and zyxin (ZYX) levels were significantly increased in the psoriasis group with CVD risk factors." (PMID 36804462, 2023). "Three novel candidates (MNDA, ZYX, and CALD1) could be potential biomarkers for predicting CVD risks in psoriasis patients." (PMID 36804462, 2023).
pulmonary sarcoidosis (1 paper, 2024). Sarcoidosis affecting the lung parenchyma. "CTSS, CYBB, FPR2, MNDA, TLR1, and TLR8 could be conducive to improving the diagnostic process and understanding the underlying mechanisms of pulmonary sarcoidosis." (PMID 39364409, 2024). "CTSS, CYBB, FPR2, MNDA, TLR1, and TLR8 could be conducive to improving the diagnostic process and understanding the underlying mechanisms of pulmonary sarcoidosis, and were further verified in PBMC samples using qRT-PCR." (PMID 39364409, 2024).
splenic marginal zone lymphoma (1 paper, 2012). Splenic marginal zone lymphoma is a rare, indolent B-cell non-Hodgkin lymphoma characterized by abnormal clonal proliferation of mature B-lymphocytes with involvement in the spleen, bone marrow and, frequently, the blood. "Myeloid cell nuclear differentiation antigen (MNDA) has recently been described as a sensitive (although not completely specific) marker of nodal and splenic marginal zone lymphomas, that might be useful both in primary sites and in the bone marrow." (PMID 23064660, 2012).
spondyloarthropathy (1 paper, 2023). A group of inflammatory rheumatic diseases associated with arthritis and enthesitis, and often involving the axial skeleton. "Also, a prior proteomic study on the spondyloarthropathy implicated MNDA as a meaningful biomarker to detect inflammatory responses earlier than other markers such as IL-6 and CRP63." (PMID 36804462, 2023).
systemic lupus erythematosus (1 paper, 2023). An autoimmune multi-organ disease typically associated with vasculopathy and autoantibody production. "In addition, MNDA is reported to be a critical gene for predicting patients with systemic lupus erythematosus complicated with atherosclerosis." (PMID 37935719, 2023).
tumor (11 papers, 2012 to 2025). "This is particularly interesting as both IFI16 and MNDA have been implicated as tumor suppressors, functioning as regulators of cell cycle and apoptotic processes." (PMID 25665578, 2015). "Subsequent to this, our discussion centers on the diverse roles of AIM2, IFI16, IFIX, and MNDA, providing a comprehensive elucidation regarding their functions and mechanisms across various tumor types." (PMID 40386782, 2025). "For example, IFIX is a DNA sensor that has anti-viral and anti-tumor activities, and MNDA regulates the transcription of IRF7 by recruiting RNA polymerase II to its promoter." (PMID 41193640, 2025). "In summary, MNDA is highly expressed in MZL except those tumor cells with plasmacytic differentiation." (PMID 38627702, 2024). "Likewise, data from the UALCAN database and Human ALTAS database confirmed that MNDA protein was also lower in tumor samples." (PMID 36101427, 2022). "These interactions may point to mechanisms by which IFI16 and MNDA could act as tumor suppressors." (PMID 25665578, 2015). "Therefore, targeting MNDA+ macrophages, restoring MNDA expression in OS cells, or inhibiting hsa-miR-889-3p could represent promising therapeutic strategies for OS, particularly in preventing bone destruction and tumor progression." (PMID 40386782, 2025). "The tumor cells were negative for CD30, Epstein–Barr virus encoded RNA (EBER), cyclin D1, CD21, myeloid cell nuclear differentiation antigen (MNDA), CD3, and CD5, while exhibiting a high Ki-67 proliferation index (about 90%)." (PMID 39891266, 2025). "This led to the selection of seven antigens found to be overexpressed in both mouse MM tumor lines under investigation and that were nearly absent in all other mouse normal tissues: KIF20A, KIF2C, MMP9, MNDA, OLFML2B, TROAP, and ULBP1." (PMID 31428586, 2019). "This group includes interferon-inducible protein 16 (IFI16), myeloid cell nuclear differentiation antigen (MNDA), absent in melanoma 2 (AIM2), and pyrin and HIN domain family member 1 (PYHIN1), each of which has been reported to be related to tumor progression." (PMID 37998338, 2023).
infection (5 papers, 2018 to 2024). The state of being infected such as from the introduction of a foreign agent such as serum, vaccine, antigenic substance or organism. "For rDEN2Δ30 infection, higher baseline expression of myeloid nuclear differentiation antigen (MNDA), and cell surface associated cellular processes such as tetraspanin CD37, integral membrane 2B (ITM2B), and genes involved in autophagy (VMP1) was associated with protection from rash." (PMID 34031380, 2021). "Latent infection of monocytes is associated with the downregulation of IFI16, MNDA, and HLA-DR." (PMID 31796538, 2019). "The three most highly upregulated genes in the conjunctiva in response to infection were integrin subunit alpha X (ITGAX), myeloid cell nuclear differentiation antigen (MNDA) and pleckstrin (PLEK) triggering." (PMID 38694515, 2024). "Whether acting as a PRR or stress-responsive transcriptional regulator, MNDA, together with the other PYHIN factors, are required for a timely response to pathogen infection or sterile inflammation." (PMID 38680493, 2024). "Therefore, IFI16, MNDA, and HLA-DR are indeed downregulated at early times during the establishment of latency, with IFI16 showing downregulation within 24 h of infection." (PMID 31796538, 2019).
cancer (4 papers, 2022 to 2025). A tumor composed of atypical neoplastic, often pleomorphic cells that invade other tissues. "The six upregulated genes (FCGR3A, LPAR5, MATK, MNDA, TMEM144, and CD84) play key immunomodulatory roles in cancer progression and metastasis." (PMID 40340807, 2025). "Myeloid cell nuclear differentiation antigen (MNDA) is a nuclear protein that regulates innate immunity, apoptosis, and cancer by interacting with many effector proteins." (PMID 36979715, 2023).
MNDA also shares sentences with these, for which no sentence is quoted: cardiovascular disease (2 papers); diffuse large B-cell lymphoma (2); marginal zone lymphoma (2); non-small cell lung carcinoma (2); allergies (1); Amoebiasis (1); asthma (1); atrial fibrillation (1); B-cell non-Hodgkin lymphoma (1); colon cancer (1); H1N1 virus infection (1); MALT lymphoma (1); mantle cell lymphoma (1); Mediterranean fever (1); melanoma (1); papilloma (1); preeclampsia (1); renal cell carcinoma (1).